CD38 (CD38 molecule)
Description:
Multifunctional transmembrane glycoprotein able to exert enzymatic activities and also to mobilize calcium, to transduce signals, to adhere to hyaluronan and to other ligands. Synthesizes cyclic ADP-ribose (cADPR), a second messenger for glucose-induced insulin secretion. Synthesizes the Ca(2+) mobilizer nicotinate-adenine dinucleotide phosphate, NAADP(+), from 2'-phospho-cADPR and nicotinic acid, as well as from NADP(+) and nicotinic acid. At both pH 5.0 and pH 7.4 preferentially transforms 2'-phospho-cADPR into NAADP(+), while preferentially cleaving NADP(+) to cADPR and ADPRP rather than into NADDP(+). Has cADPR hydrolase activity. Functions also as a receptor that binds the ligand CD31 on endothelial cells, promoting lymphocyte activation, proliferation, and migration across the endothelial barrier. Involved in the regulation of crucial dendritic cell functions acquired at the mature stage, such as CCL21-driven migration, survival, and Th1-polarizing activity. In lamina propria T lymphocytes, CD38/CD31 cognate interactions initiate a multistep signaling pathway resulting in activation of LCK anf LAT, followed by cytokine release.
Synonyms: ADPRC 1; cADPR1; ADPRC1
Tractability: Small molecule: a structure with a bound ligand is known; a high-quality ligand is known; it has a high-quality binding pocket. Antibody: an approved drug acts on it; UniProt places it where antibodies can reach, with high confidence; its Gene Ontology location is reachable by antibodies, with high confidence; UniProt predicts a signal peptide or a membrane-spanning region; the Human Protein Atlas places it where antibodies can reach. PROTAC: ubiquitination databases record sites on it; its protein half-life has been measured; a small molecule that binds it is known.
Target class: Enzyme
Gene: Protein-coding gene on chromosome 4 (15,778,275 to 15,853,232, forward strand). Ensembl gene ENSG00000004468.
Subcellular location: Cell surface; Cell membrane
Subcellular location (Human Protein Atlas): Plasma membrane
Pathways (Reactome):
Metabolism: Nicotinate metabolism
Gene Ontology:
Molecular function: NAD+ nucleosidase activity, cyclic ADP-ribose generating; signaling receptor activity; hydrolase activity, acting on glycosyl bonds; identical protein binding; phosphorus-oxygen lyase activity
Biological process: B cell receptor signaling pathway; negative regulation of apoptotic process; negative regulation of DNA-templated transcription; positive regulation of B cell proliferation; positive regulation of DNA-templated transcription; response to xenobiotic stimulus; T cell activation; apoptotic signaling pathway; nicotinate metabolic process; signal transduction; artery smooth muscle contraction; female pregnancy; long-term synaptic depression; negative regulation of bone resorption; negative regulation of neuron projection development; positive regulation of cell growth; positive regulation of cell population proliferation; positive regulation of cytosolic calcium ion concentration; positive regulation of insulin secretion; positive regulation of vasoconstriction; response to cytokine; response to estradiol; response to hormone; response to hydroperoxide; response to hypoxia; and 3 more
Cellular component: cell surface; extracellular exosome; plasma membrane; membrane; basolateral plasma membrane; nuclear membrane
Genetic constraint (gnomAD): Loss-of-function variants: 16 observed, 18.81 expected, observed/expected ratio (o/e) 0.85, 90% interval 0.57 to 1.29. The upper end of that interval is the gene's LOEUF score, 1.29, which puts it in group 5 of 6, group 1 being the genes least tolerant of losing a copy. Missense variants: 246 observed, 261.16 expected, observed/expected ratio (o/e) 0.94, 90% interval 0.85 to 1.05. Synonymous variants: 96 observed, 104.28 expected, observed/expected ratio (o/e) 0.92, 90% interval 0.78 to 1.09.
Homologues: Orthologues: chimpanzee CD38 (99% identical), macaque CD38 (92% identical), mouse Cd38 (58% identical), rat Cd38 (58% identical), dog CD38 (57% identical), pig CD38 (50% identical), tropical clawed frog cd38 (34% identical). Paralogues in human: BST1 (34% identical).
Diseases named in the same sentence as CD38 in open-access papers:
CD38 is named in the same sentence as 481 diseases in open-access papers, as found by Europe PMC text mining. Sharing a sentence is not in itself a finding about the gene and the disease. The quoted sentences say what the papers report.
multiple myeloma (814 papers, 2006 to 2026). "One of the most frequently mentioned is the reduction of CD38 expression on myeloma cells and the clonal selection of CD38dim tumor cells caused by treatment with anti-CD38 antibodies." (PMID 39857790, 2025). "For isatuximab, transcriptome analyses of NK cells cocultured with myeloma cells revealed deregulated expression of 70 genes linked to chemotaxis, cytolysis, and defense response, reflecting activation via Fc binding and CD38 transmembrane signaling." (PMID 40444214, 2025). "We modelled the loss of CD38 expression in myeloma as a temporary process that will fully reverse if treatment stops, which is consistent with clinical observation." (PMID 40788967, 2025). "The efficacy of CD38 monoclonal antibody (mAb)-based quadruplet regimens versus triplet regimens in newly diagnosed multiple myeloma (NDMM) patients with high-risk cytogenetics remains controversial." (PMID 41567224, 2025). "These challenges are common; for example, a study on the therapeutic mAb daratumumab found that the mAb saturates the myeloma cell marker CD38 and interferes with the diagnostic CD38 antibodies." (PMID 39745446, 2025). "In our model myeloma cells resist the effect of Dara via loss of CD38 expression, albeit at the cost of reduced fitness." (PMID 40788967, 2025). "Isatuximab is a monoclonal antibody targeting the CD38 protein on myeloma cells, causing cell death through various immune-mediated mechanisms." (PMID 40124649, 2025). "In this work we focus on one known resistance mechanism, in which myeloma cells resist Dara via loss of CD38 expression." (PMID 40788967, 2025). "Daratumumab, an anti‐CD38 monoclonal antibody, is used for multiple myeloma (MM) treatment, and causes immunosuppression by targeting CD38‐expressing normal lymphocytes." (PMID 39034465, 2024). "Patients with multiple myeloma, especially those treated with anti-CD38 mAbs, are considered high risk for breakthrough COVID-19 due to suboptimal antibody response following vaccination and underlying immune deficiency from the disease itself." (PMID 38092996, 2024). "Overall, we conclude that loss of CD38 in isolation leads to limited remodeling of the myeloma surface proteome." (PMID 40453054, 2024). "Daratumumab targets CD38 on myeloma and some immune cells, causing immune activation and infusion-related reactions (fever, chills, respiratory issues), as well as hematologic toxicities (neutropenia, thrombocytopenia, anemia), increasing infection risk." (PMID 39065666, 2024). "The efficacy of the anti-CD38 monoclonal antibody in delaying progression to multiple myeloma was assessed in high-risk MGUS or low-risk SMM patients in the phase 2 study, D-PRISM (Precision Intervention Smoldering Myeloma, NCT03236428)." (PMID 39065751, 2024). "The reduction or loss in CD38 cell surface expression is an important mechanism involved in resistance to anti-CD38 MoAbs in Multiple Myeloma." (PMID 37532787, 2023). "Multiple therapeutic approaches that target CD38 in multiple myeloma, melanoma and other CD38-associated malignancies are currently investigated, with the prevailing mechanism attributed to antibody-mediated cytolysis and phagocytosis." (PMID 38086958, 2023). "CCDC26, a long non-coding RNA gene, and CD38, a gene associated with activation and multiple myeloma, were suppressed, indicating that these cells were differentiated and no longer displaying the leukemia phenotype." (PMID 36982186, 2023). "Research into PC dyscrasias revealed that the processes set off by anti-CD38 monoclonal antibodies ultimately cause the immune system to be activated against myeloma cell growth." (PMID 37563241, 2023). "This agent, consisting of 2 (attenuated) IFNα2b molecules fused to the Fc portion of a humanized, anti-CD38 mAb, is designed to induce direct antiproliferative effects on myeloma cells and cause both direct and indirect immune cell activation." (PMID 36944635, 2023).
multiple myeloma (continued). "They demonstrated in vitro that VD is a key molecule for restoring and maintaining the effector functions of myeloma-associated macrophages and that VD supplementation in combination with IMiDs can enhance the therapeutic efficacy of anti-CD38 antibodies." (PMID 38201971, 2023). "With the increased focus on beyond the first year of diagnosis in the anti-CD38 monoclonal antibody era, it is essential to perform Holter monitoring in patients with AL amyloidosis to identify and intervene with high-risk patients." (PMID 38068514, 2023). "In a recently published case of ABMR (associated with smoldering myeloma), a 9-month course of CD38 antibody daratumumab was reported to successfully reverse severe chronic active ABMR." (PMID 35395951, 2022). "Specifically, TNFSF13B expression had close interactions with macrophage marker genes, namely, TLR and S100A9 genes; their receptor genes, TNFRSF13B and TNFRSF17, showed significant associations with the myeloma-related genes CD38, SDC1, and MYEOV." (PMID 34150664, 2021). "The greatest therapeutic success so far has been in multiple myeloma using CD38 inhibitors as an antibody-based therapy to target white blood cells in the bone marrow that cause the disease and where CD38 is found on the cell surface." (PMID 34885748, 2021). "Higher CD38 expression in AL amyloidosis is associated with the worst event-free survival probably because it is associated with more severe cardiac involvement, as shown by higher serum NT-proBNP concentrations." (PMID 33806310, 2021). "One group tested a tandem bispecific CAR T therapy targeting both BCMA and CD38 linked to 4-1BB and CD3ζ costimulatory domains as part of a phase 1 trial to assess efficacy, durability, and safety profiles in the R/R multiple myeloma setting." (PMID 32899464, 2020). "We found that incubation of bone marrow samples with CD38-specific Nb-CAR-NK cells mediates a significantly higher loss of myeloma cells than incubation with control Nb-CAR-NK cells." (PMID 32013131, 2020). "In multiple myeloma, CD38 is implicated in promoting more aggressive immunosuppressive MDSCs and Treg." (PMID 32709019, 2020). "For example, the pathogenic role of CD38 have been implicated in multiple myeloma (MM), where tumor cells exhibit high surface expression of CD38." (PMID 32709019, 2020). "Higher CD38-expression was associated with slower progression to symptomatic and relapsed myeloma and better overall survival in the latter two entities." (PMID 30079070, 2018). "High CD38-expression is associated with lower risk of progression from asymptomatic to symptomatic and symptomatic to relapsed myeloma and better overall survival in the latter two." (PMID 30079070, 2018). "First, lower CD38-expression is associated independently with faster progression of asymptomatic to symptomatic and symptomatic to relapsed myeloma." (PMID 30079070, 2018). "The same trend can also be seen for the subgroup of patients with AL-amyloidosis: lower CD38-expression is found with underlying asymptomatic myeloma compared to MGUS, being significant for GEP (p = 0.02) and flow cytometry (p = 0.008), respectively." (PMID 30079070, 2018). "Here, by using the multiple myeloma (MM)-associated CD38 molecule as target molecule, we tested the feasibility and utility of a doxycycline (DOX) inducible Tet-on CD38-CAR design to control the off-target toxicities of CAR T cells." (PMID 29847570, 2018). "In AL-amyloidosis, we found the opposite association: higher CD38-expression is associated with adverse survival." (PMID 30079070, 2018). "The nanobodies reported here thus hold promise as new diagnostic and potential therapeutic tools for multiple myeloma and other CD38-expressing malignancies." (PMID 29084989, 2017). "Similarly, anti‐CD38 therapy with daratumumab for multiple myeloma has been associated with reduced antibody response to SARS‐CoV‐2 mRNA vaccine." (PMID 40693453, 2025).
multiple myeloma (continued). "We suggest that EPOCH combined with other less cytotoxic myeloma drugs, such as anti-CD38 antibodies or proteasome inhibitors, is a possible option for anaplastic myeloma, and perhaps also for other rapid growing variants of multiple myeloma, e.g., plasma cell leukaemia." (PMID 40914992, 2025). "In addition, the trogocytic transfer of complexes consisting of CD38 and daratumumab from the myeloma cell surface to immune effector cells is an additional important mechanism for CD38 antigen loss on both myeloma cells and immune cells." (PMID 38284882, 2024). "Relevant studies suggest that the mechanisms of multiple myeloma resistance to daratumumab are associated with immune escape, as relapsing patients show stable expression of unmutated CD38 on cancer cells, which preserves their ability to be targeted by daratumumab." (PMID 38826403, 2024). "Since then, more information has emerged on the importance of CD38, specifically on its loss resulting in impaired immune responses, metabolic disturbances, and behavioral modifications in mice, and on it being also a marker of human leukemias and myelomas." (PMID 38817957, 2023). "While they are already in clinical use for the treatment of multiple myeloma, the presence of CD38+ B cells was associated with good clinical outcomes with O + D, and therefore inhibition in solid cancers may not be desirable." (PMID 37365284, 2023). "Finally, another important issue potentially hampering the safety of CD38 inhibition in SSc is the higher risk of infection and sepsis associated with this treatment as shown by studies in multiple myeloma." (PMID 36618427, 2022). "Additionally, CD38 catalyzes NAD+ to cylic ADP‐ribose (cADPr), a Ca2+ releasing second messenger.CD38 protein is a marker of cell activation and associated with a variety of biological functions and diseases, including leukemias, myelomas and diabetes." (PMID 35441488, 2022). "Upregulation of mitochondrial biogenesis, CD38-driven mitochondrial trafficking, mutations in mitochondrial genes and OxPhos stimulation are also involved in the mechanism with which myeloma adapts metabolically and maintains bioenergetic plasticity." (PMID 35794249, 2022). "Using stably transfected Chinese hamster ovary cells expressing individual myeloma-associated antigens revealed that two antibodies bind CD38 and intercellular adhesion molecule-1 (ICAM-1), respectively, and 7 antibodies target yet unknown antigens." (PMID 35784366, 2022). "From investigated gene expression-based factors including proliferation, only the UAMS70-gene-score showed an association with CD38-expression in symptomatic myeloma patients (p < 0.001); surprisingly, high risk correlated with significantly higher CD38-expression." (PMID 30079070, 2018). "By contrast, high CD38-expression is associated with adverse survival in AL-amyloidosis." (PMID 30079070, 2018). "Importantly, without the addition of Fc crosslinking agents or effector cells, isatuximab induced homotypic aggregation-associated multiple myeloma cell killing in a CD38-dependent manner." (PMID 31548533, 2017). "A recent study also suggested that CD38 enzymatic activity may be associated with immunosuppression in patients with multiple myeloma patients, due to its involvement in the production of immunosuppressive adenosine (ADO)." (PMID 31548533, 2017). "However, we hypothesized that, given its enzymatic activity and role as a cellular differentiation marker, loss of CD38 on its own may influence surface expression of other myeloma antigens." (PMID 40453054, 2024). "The benefit of associating anti-CD38 monoclonal antibodies to proteasome inhibitor (PI)/immunomodulatory agent (IA) and dexamethasone in the treatment of patients with relapsed or refractory multiple myeloma (MM) remains unclear." (PMID 38672988, 2024).